CDX2 (caudal type homeobox 2)
Diseases named in the same sentence as CDX2 in open-access papers (continued):
Sharing a sentence is not in itself a finding about the gene and the disease.
cholangiocarcinoma (9 papers, 2014 to 2025). A carcinoma that arises from the intrahepatic biliary tree (intrahepatic cholangiocarcinoma) or from the junction, or adjacent to the junction, of the right and left hepatic ducts (hilar cholangiocarcinoma). "Both primary cholangiocarcinomas in the test set showed a CK20-/CK7+/CDX2-/CA125- immunophenotype, indicating a low probability of colorectal, ovarian, and pancreatic origin." (PMID 33852640, 2021). "Excluding tumors of unknown primary origin, GI and PBS-originating tumors, and cholangiocarcinomas, CDX2 was positive in only 4 out of 38 cases (10.5%)." (PMID 40751531, 2025). "Therefore, immunohistochemical studies of cytokeratin (CK) 7, CK20, and Caudal-type homeobox transcription factor 2 (CDX2) were performed to distinguish between cholangiocarcinoma and metastatic liver cancer." (PMID 30658608, 2019). "In gastric and cholangiocarcinoma cell lines, proinflammatory cytokines including IL-1β, IL-6, and TNF-α have all been reported to induce Cdx2 gene expression." (PMID 26460825, 2015). "Although there is no characteristic panel of antibodies that are pathognomonic for cholangiocarcinoma, tumors of biliary epithelial origin tend to express CK7 and sometimes CK20 although they lack CDX2 expression." (PMID 25120936, 2014). "The atypical glands were positive for CK7, while negative for CK20, CDX-2, and TTF-1, consistent with intrahepatic cholangiocarcinoma." (PMID 32724695, 2020).
dysplasia (9 papers, 2011 to 2024). A usually neoplastic transformation of the cell, associated with altered architectural tissue patterns. "CDX2 is a highly sensitive marker of intestinal metaplasia; thus, these data indicated that type II CP is significantly associated with dysplasia and intestinal metaplasia in BE as compared with type I." (PMID 25621687, 2015). "Gastric intestinal metaplasia is a common complication for H. pylori-induced metaplasia-dysplasia-carcinoma sequence, which was characterized by increased CDX2 and/or MUC2 expression, which has been received PPI treatment." (PMID 39575386, 2024). "Reinforcing a role of CDX2 in this carcinogenic pathway, we observed a high percentage of CDX2 positivity in dysplasia and BA." (PMID 27766003, 2016). "CDX1/CDX2 genes seem to have a key role in intestinal dysplasia reprogramming." (PMID 38542354, 2024). "However, CDX2 became dramatically expressed in BE, and its expression was increased with the development of dysplasia; CDX2 expression was downregulated but still maintained at high levels in EAC." (PMID 36994101, 2023). "However, the expression of CDX2 gradually declined in the process of intestinal metaplasia-dysplasia-GC and the molecular mechanisms leading to the inactivation of CDX2 remain unclear." (PMID 23408490, 2013). "Specifically, during normal esophageal squamous, BE metaplasia, dysplasia, and EAC progression there is a progressive increase in TFF2, TFF3, MUC2, MUC5AC, MUC6, CDX2 with the development of intestinal metaplasia." (PMID 36994101, 2023). "In this study we describe the expression of two transcription factors, CDX2 and SOX2, in a series of esophageal columnar metaplasia without IM (CLES) and with IM as well as in dysplasia and BA." (PMID 27766003, 2016).
neuroendocrine carcinoma (9 papers, 2020 to 2025). A malignant neuroendocrine neoplasm composed of cells containing secretory granules that stain positive for NSE and chromogranin. "Further, CDX-2 negativity can exclude neuroendocrine cancer of the intestine." (PMID 41245381, 2025). "The histological examination of the biopsy showed the presence of poorly differentiated neuroendocrine carcinoma (NEC), whose immunophenotype was reported as CK 19+, CK7−, CK20−, CDX2+, synaptophysin+, Ki67 90%." (PMID 40141766, 2025). "CDX2 can be expressed in neuroendocrine carcinomas of pancreas and non-GI tract high-grade neuroendocrine carcinomas, such as those of the bladder and lung." (PMID 33504059, 2021). "Negative results were obtained for cytokeratin 20, CDX2, CD56, S100, and neuroendocrine markers such as synaptophysin, which excluded other tumor types, including neuroendocrine carcinoma and adenocarcinoma." (PMID 39860304, 2025).
osteoporosis (9 papers, 2016 to 2025). A condition of reduced bone mass, with decreased cortical thickness and a decrease in the number and size of the trabeculae of cancellous bone (but normal chemical composition), resulting in increased fracture incidence. "The OR was calculated for the GATA/CDX2 block, showing a significant association with osteoporosis, with an OR of 1.316 and a P value of 0.018." (PMID 39072539, 2024). "Apart from osteoporosis, CdX-2 polymorphism also plays an important role in immune-related conditions." (PMID 36490235, 2022). "Since then, a large number of studies have reported that VDR gene mutations (such as FokI (rs10735810), BsmI (rs1544410) and Cdx2 (rs11568820) were related to osteoporosis risk." (PMID 32627819, 2020). "Although several related meta-analyses have reported the associations between VDR BsmI, FokI, and Cdx2 polymorphisms and the risk of osteoporosis." (PMID 32627819, 2020). "Six previous meta-analyses have been published to analyze VDR BsmI, FokI, and Cdx2 polymorphisms on osteoporosis risk." (PMID 32627819, 2020). "Previous evidence also demonstrated high LD of CdX-2 and GATA, resulting in the association of different haplotypes and their outcomes in the Dutch population and patients with osteoporosis." (PMID 36490235, 2022). "A total of 43 studies were included in the current meta-analysis, of which 34 studies explored the association between VDR BsmI and osteoporosis risk, 19 studies reported VDR FokI polymorphism, and four studies related to VDR Cdx2 polymorphism." (PMID 32627819, 2020). "In this study, we investigated the relationship between sarcopenia (evaluated in term of fibers atrophy), VDR protein expression and TaqI/Cdx2/FokI VDR genotypes in an Italian cohort of osteoporosis(n=44) and osteoarthritis (n=55) patients." (PMID 30574409, 2018). "In this study, we investigated the relationship between sarcopenia (evaluated in term of fibers atrophy), vitamin d receptor protein expression and TaqI/Cdx2/FokI VDR genotypes in an Italian cohort of osteoporosis(n=44) and osteoarthritis (n=55) patients." (PMID 30574409, 2018). "The literature data on the relationship between the BsmI and Cdx2 polymorphisms of the VDR gene and the development of osteoporosis are ambiguous and sometimes contradictory, so it was decided to check their impact on the risk of developing osteoporosis in the Polish population." (PMID 39859195, 2025). "Moreover, due to the limited number of studies, we did not perform subgroup analyses in the pooled analysis of VDR Cdx2 polymorphism and osteoporosis risk." (PMID 32627819, 2020).
pancreatic cancer (9 papers, 2012 to 2024). "This is possibly because CDX2 regulates the tumor suppressor gene miR-615-5p and inhibits pancreatic cancer cell proliferation." (PMID 34367978, 2021). "In pancreatic cancer cells, CDX2 inhibits cell proliferation by directly repressing cyclin D1 transcriptional activity." (PMID 30631044, 2019). "In CK7+/CK20+ tumors, CDX2 expression was observed in 22 of 24 (92%) colorectal, 21 of 28 (75%) gastric, and 2 of 7 (29%) pancreatic carcinomas." (PMID 22268990, 2012). "In the patient's case, the tumor's immunohistochemical profile, specifically being TTF-1 positive (associated with pulmonary tumors) and CDX2 negative (associated with GI and pancreatic tumors), strongly suggests a lung origin." (PMID 39130860, 2024). "Immunohistochemistry, such as SMAD4, MUC5AC, and CDX2 expression, may be useful to distinguish them; SMAD4 nuclear expression is more preserved in iCCA compared with pancreatic cancer." (PMID 34201284, 2021). "In contrast, CDX2 and MUC5AC expression are more common in pancreatic cancer compared with iCCA." (PMID 34201284, 2021).
rectal adenocarcinoma (9 papers, 2014 to 2025). "CDX2 positivity (rectal adenocarcinoma) and CD117 positivity (GIST) was seen in one sample each." (PMID 25608976, 2014). "From 2003, many reports document CDX2 and CK20 positivity in almost all rectal adenocarcinomas, but negativity in endometrial carcinoma." (PMID 26783488, 2015). "At her next colonoscopy, a palpable posterior rectal mass was biopsied confirming rectal adenocarcinoma with positive caudal type homeobox 2 (CDX-2) and negative paired box gene 8 (PAX-8)." (PMID 40678160, 2025). "The immunophenotype of the patient was highly consistent with CK7 (+), CK20 (−), and CDX-2 (−), confirming that the rectal adenocarcinoma was not primary but a metastatic ICC." (PMID 40538855, 2025). "AMACR knockdown did not affect CDX2 expression, consistent with it being downstream of CDX2.To validate the relationship between CDX2 and AMACR in human CRCs, we next evaluated The Cancer Genome Atlas (TCGA) for CDX2 and AMACR in colon and rectal adenocarcinomas (COADREAD)." (PMID 33755595, 2021). "Positive staining for PSA and P501s is commonly seen in prostate adenocarcinoma, unlike rectal adenocarcinoma which distinguishes with positive CDX2, CK20 and beta-catenin staining and negative for PSA and P501s." (PMID 31014272, 2019). "Rectal adenocarcinoma, unlike prostatic adenocarcinoma, shows positive staining for b-catenin, caudal-related homeobox 2 (CDX2) and carcinoembryonic antigen(CEA) but negative staining for PSA, PSAP, P501S." (PMID 24555830, 2014). "Most commonly gained or lost genes seen in rectal adenocarcinoma (FLT3, CDX2, GNAS, BCL2, SMAD4, MALT1) are not found in rectal squamous cell carcinoma." (PMID 36357817, 2023).
squamous cell carcinoma (9 papers, 2009 to 2025). A carcinoma arising from squamous epithelial cells. "CDX2 positivity was noted in all adenocarcinomas, while P63 positivity was noted in all squamous cell carcinomas and focally positive in adenocarcinomas with squamous differentiation." (PMID 40361397, 2025). "No Cdx2 expression was detected in either squamous epithelia of the proximal esophagus or squamous cell carcinomas." (PMID 19664209, 2009). "Squamous cell carcinoma tissues express CK5/6 and p63, and adenocarcinoma tissues express CK7; villin and CDX2 are not negative in this tissue type." (PMID 37724114, 2023).
urothelial carcinoma (9 papers, 2007 to 2025). A malignant neoplasm derived from the transitional epithelium of the urinary tract (urinary bladder, ureter, urethra, or renal pelvis). "In this case, the panel was immunopositive for Muc-2, CK7 and CK20 and immunonegative for CDX-2; this, together with the histological findings, characterized a mucus-secreting urothelial carcinoma." (PMID 18094900, 2007). "In rare cases, urothelial carcinoma with glandular differentiation or metastatic colorectal adenocarcinoma may exhibit overlapping immunophenotypes; however, the absence of GATA3 and CDX2 in this case helped exclude those possibilities." (PMID 40662003, 2025). "Urothelial carcinoma with glandular differentiation is CK7 positive and villin, CDX2, and CK20 negative while metastatic adenocarcinoma of the colon shows positive staining for villin, CDX2, and negative for CK20 and CK7." (PMID 38846211, 2024).
bladder adenocarcinoma (8 papers, 2006 to 2024). "The available evidence suggests that an immunohistochemical panel of CK7, CK20, CDX2, beta-catenin, thrombomodulin and Villin may best distinguish primary bladder adenocarcinomas from metastases." (PMID 17040576, 2006). "A significant number of PBA cases (one-third) and MCA cases (8.3%) exhibited strong CK7 expression, suggesting a limited ability to distinguish PBAs from secondary bladder adenocarcinomas based on CK7 and CDX-2." (PMID 38260844, 2023). "IHC can be helpful, as bladder adenocarcinoma is positive for CK7, CK20, CDX2, and thrombomodulin and negative for nuclear β-catenin." (PMID 27006847, 2016).
mucinous tumors (8 papers, 2019 to 2025). "Decreased expression of CDX2 is associated with mucinous tumors, lymph node involvement, and high-grade tumors." (PMID 35240026, 2022). "Both CK20 and CDX2 were expressed in mucinous tumors, and commonly used for distinguish metastatic ovarian mucinous tumors from primary ovarian mucinous tumors." (PMID 35387670, 2022). "Regarding mucinous tumors arising from the colon and appendix, the most sensitive marker is CDX2 (91.7%), while the most specific is SATB2 (98.0%)." (PMID 31771640, 2019). "For instance, immunohistochemical markers like CK7, CK20, Villin, CDX-2, MUC-2, and PAX8 are employed for the differential diagnosis of ovarian primary mucinous neoplasms (OPMN) and ovarian secondary peritoneal pseudomyxoma." (PMID 40486880, 2025). "MOC shares common features with other mucinous tumors, including gastrointestinal metastases, such as positive CK20, CEA, Ca19-9 and CDX2 staining." (PMID 36900244, 2023). "Gastrointestinal and mucinous tumors often express markers of gastrointestinal differentiation: CK20 and CDX2, while OSMC expressed the markers of Mullerian epithelium: ER, PR, CA125, mesothelin." (PMID 36670456, 2023). "The negativity for CK20, CDX2, and WT1 and positivity for ER and PR is useful in routine practice in differentiating borderline seromucinous tumors from borderline serous and mucinous tumors." (PMID 33736662, 2021).
teratoma (8 papers, 2012 to 2025). A non-seminomatous germ cell tumor characterized by the presence of various tissues which correspond to the different germinal layers (endoderm, mesoderm, and ectoderm). "Intense and diffuse expression of CDX2 should raise suspicion for metastasis from a gastrointestinal primary, with the rare exception of teratoma-associated MBT." (PMID 28025670, 2017). "Intestinal epithelium (endoderm tissue) expressing CDX-2 developed in the teratoma; some of these tissues also showed HNF3β/FOXA2 immunoreactivity (data not shown)." (PMID 25111735, 2014). "Scalloped glands, subepithelial clefts, cellular stroma, and histiocyte aggregates, along with immunohistochemical markers such as CK7, CK20, CDX2, and SATB2, can aid in determining the source of PMP and assessing its biological behavior from various origins (excluding teratoma-associated tumors)." (PMID 38672528, 2024). "Two of the mucinous cystadenomas were associated with teratoma; both were consistently negative for CK20, CDX2, and PAX8." (PMID 31771640, 2019). "In this case, the patient’s teratoma contained various types of epithelium, and the majority of cystic lesion was shown to be lined with mucinous epithelium similar to lower intestinal tract by histological and immunological examination (CK7-/CK20+/CDX2+)." (PMID 27938333, 2016). "We have demonstrated that variable CDX2 reactivity could be detected in the YST elements of mixed germ cell tumors with YST components in up to 40% of the cases and in mature colonic type epithelium in mature teratoma." (PMID 22848863, 2012). "SATB2 has been proven to be negative in POMNs with the exception of cases arising from teratoma, making it a superior marker in comparison to CK20 and CDX2." (PMID 31771640, 2019).
acute myeloid leukemia (7 papers, 2012 to 2025). Acute myeloid leukemia (AML) is a group of neoplasms arising from precursor cells committed to the myeloid cell-line differentiation. "Previous studies have shown that the proliferation of acute myeloid leukemia cells is compromised when CDX2 is knocked down, and, conversely, that inducing Cdx2ex vivo in hematopoietic progenitors increases self‐renewal." (PMID 33960108, 2021). "The caudal-related homeobox gene CDX2 is not expressed in normal hematopoietic stem cells (HSCs), but is expressed in ~90% of acute myeloid leukemia (AML) patients, as well as those with high-risk myelodysplastic syndrome (MDS) and advanced chronic myeloid leukemia (CML)." (PMID 32541670, 2020). "Beside the upper digestive tract, CDX2 is also ectopically expressed in 80% of acute myeloid leukemia (AML) irrespective of the cytogenetic group but correlating with disease burden." (PMID 34759958, 2021).
endometrioid carcinoma (7 papers, 2016 to 2023). "However, the LCNEC and, to a lesser extent, the endometrioid carcinoma also expressed CDX2, a homeobox protein expressed in intestinal epithelial cells and related proliferation." (PMID 34342838, 2022). "In both endometrioid carcinoma and ACP, positivity for β-catenin (nuclear), CD10, and CDX2 was observed around several ghost cell-keratinizing areas, consistently with their derivation from MorM/WS." (PMID 33666744, 2021). "Immunohistochemistry for β-catenin, CD10, CDX2, ki67, p63, CK5/6, CK7, CK8/18, CK19, and pan-hard keratin was performed; 10 cases of endometrioid carcinomas with conventional squamous differentiation were used as controls." (PMID 33666744, 2021). "CDX2 positivity was strong and homogenous and not confined to substructures like the reported CDX2 positive morules in conventional endometrioid adenocarcinoma." (PMID 28494767, 2017). "Borderline seromucinous tumors and endometrioid carcinoma with mucinous differentiation are usually positive for IHC stains CK7, ER, PR and CA125 as well as PAX8 and are usually negative for CK20, CDX2 and WT1." (PMID 33736662, 2021).
intestinal type adenocarcinoma (7 papers, 2008 to 2023). An adenocarcinoma arising from epithelium which has undergone intestinal metaplasia. "Similar to this case, cervical invasive intestinal-type adenocarcinomas show diffuse expression of CDX2, CK20, CEA, and p16." (PMID 24307962, 2013). "Morphologically, CDX2- and PAX8-expressing subtypes resembled intestinal-type adenocarcinoma and clear cell carcinoma (occurring in gynecological organs), respectively." (PMID 37510152, 2023). "Immunohistochemistry for intestinal type adenocarcinoma is known to reveal positivity for pancytokeratin, EMA, B72.3, BerEP4, Leu M1, CK20, CDX2 and variable CK7 immunoreactivity." (PMID 18492272, 2008). "This is to be distinguished from primary sinonasal intestinal-type adenocarcinoma, which may share similar morphology and immunophenotyping, such as immunoreactivity for CK20 and cdx2." (PMID 31010194, 2019).
metastatic colorectal cancer (7 papers, 2017 to 2025). "Diagnosis relied on recognition of intestinal-type morphology and confirmatory immunohistochemistry, particularly CK20 and CDX2 positivity, while excluding metastatic colorectal cancer." (PMID 41463238, 2025). "Patient characteristics according to caudal-type homeobox 2 status in a population-based cohort of metastatic colorectal cancer with CDX2 status available (n = 452)." (PMID 32117703, 2020). "This chemotherapy regimen is commonly used to manage metastatic colorectal cancer, but also administered to CUP patients with K20+/K7–/CDX2+ IHC signature." (PMID 34178989, 2021). "Immunocytochemical positivity for CK20 and CDX-2 and negativity for CK7, CK5/6, P63 and TTF-1 confirmed this to be metastatic colorectal cancer." (PMID 29029440, 2017).